LCN2 (lipocalin 2)
Diseases named in the same sentence as LCN2 in open-access papers (continued):
Sharing a sentence is not in itself a finding about the gene and the disease.
mastitis (5 papers, 2017 to 2024). Inflammation of breast tissue during lactation or postpartum due to an obstructed duct or infection. "Recently, it has been shown that secreted human LCN2 cloned into bovine mammary epithelial stem cells actively inhibits growth of mastitis-causing S. aureus as well." (PMID 28791009, 2017). "Two additional candidate genes chosen from our previous study of postpartum disease (CATHL6 and LCN2) also were upregulated (B-Y p ≤ 0.05) at the onset of mastitis." (PMID 33195534, 2020). "It is worth acknowledging that a less conservative estimate (uncorrected p ≤ 0.05) indicated upregulation of one other candidate gene (C5AR1) at the onset of mastitis, and ongoing upregulation of LCN2 and PGLYRP1 at sampling points 2 and 3, respectively." (PMID 33195534, 2020). "On the other hand, the initial log fold-changes of CATHL6 (4.70 ±1.70) and LCN2 (3.75 ±1.26) quickly diminished such that they were upregulated only at the onset of mastitis." (PMID 33195534, 2020). "Three genes (PGLYRP1, CATHL6, and LCN2) were differentially expressed between sampling points for mastitic cows when comparing samples from the onset of mastitis to those from sampling points 2 or 3 (B-Y p ≤ 0.05)." (PMID 33195534, 2020). "As a fourth hallmark of mastitis, the local inflammatory protein profile was measured on mammary gland lysates with particular attention to the neutrophil-associated markers MIP-2 (IL-8), G-CSF, and LCN2." (PMID 38204128, 2024). "Of the four genes (C5AR1, CATHL6, LCN2, and PGLYRP1) with evidence of upregulation in cows with mastitis, three of those genes (CATHL6, LCN2, and PGLYRP1) were investigated due to their previously identified association with postpartum disease." (PMID 33195534, 2020). "Complementing the local cytokine profiles, we at first evaluated LCN2 and CHI3L1 as potential in vivo and in vitro innate immunity modulators in the context of mastitis." (PMID 28791009, 2017). "Other authors found a significant impact of the polymorphisms in the lipocalin-2 (LCN2) gene on the average SCS of milk, but not on the milk yield, protein, fat and lactose contents, or the incidence of mastitis in cows." (PMID 33902174, 2022). "Moreover, during S. aureus-induced mastitis, a salient finding was that neutrophil recruitment only caused a limited induction of local CHI3L1 and even no increase in mammary LCN2 compared to sham inoculation." (PMID 28791009, 2017). "We identified three genes (CATHL6, LCN2, and PGLYRP1) that were upregulated during the early stages of mastitis regardless of differences in breeds, parities, days in milk, production levels and pregnancy status." (PMID 33195534, 2020). "Moreover, our data indicated that neutrophils can be ruled out as the (only) source of LCN2 and CHI3L1, as a strong increase of both innate immune signals was absent in experimental S. aureus murine mastitis." (PMID 28791009, 2017).
neuropathy (5 papers, 2021 to 2025). A disorder affecting the nervous system that manifests with pain, tingling, numbness, and/or muscle weakness. "Recent studies have provided essential evidence of LCN2 as a major player linked to metabolism, inflammation, and neuropathy." (PMID 33613327, 2021). "Noteworthy, other carcinomas, neuropathy, and metabolic diseases have a greater impact on the level of LCN2 in the blood, and the detection of stool may be more beneficial for diagnosis value of UCAC in subsequent use." (PMID 35111677, 2021). "Moreover, in participants with T2D, Spearman’s analysis showed that serum LCN2 level positively correlated to TCNS score, which reflects neuropathy severity (r = 0.438, P = 0.000)." (PMID 34636748, 2021). "Moreover, serum LCN2 levels positively correlated to TCNS scores, which reflects neuropathy severity (r = 0.438, P = 0.000)." (PMID 34636748, 2021).
osteosarcoma (5 papers, 2021 to 2025). A usually aggressive malignant bone-forming mesenchymal neoplasm, predominantly affecting adolescents and young adults. "Accordingly, we chose HOS and U2OS cells in all subsequent experiments to investigate the role of LCN2 in mechanisms underlying modulation of osteosarcoma metastasis." (PMID 34202288, 2021). "Here, we tested the potential of LCN2 on human osteosarcoma metastasis and also investigated its underlying mechanisms." (PMID 34202288, 2021). "Our recent study has shown that LCN2 suppresses MET expression to inhibit osteosarcoma cell metastasis." (PMID 36428800, 2022). "Conclusively, LCN2 inhibits osteosarcoma cell metastasis by suppressing MET via the MEK–ERK pathway." (PMID 34202288, 2021). "In this study, we demonstrated that higher LCN2 inhibited cellular motility, migration, and invasion of osteosarcoma cells." (PMID 34202288, 2021). "This new discovery illustrates the involvement of the MEK–ERK pathway and downstream MET on migration of osteosarcoma, which in turn illustrates the pertinence of further studying LCN2 related to anti-metastasis for human osteosarcoma." (PMID 34202288, 2021). "Manipulation of LCN2 levels influenced the migratory potential of osteosarcoma cells as cellular migration was enhanced by transfecting with vectors containing a constitutively active LCN2 cDNA and recombinant human LCN2." (PMID 34202288, 2021). "Higher neutrophil-derived cytokine lipocalin-2 (LCN2) expression possesses a versatile role in a myriad of cancers, but little is known about the role of LCN2 on osteosarcoma metastasis." (PMID 34202288, 2021). "Conclusively, LCN2 inhibits osteosarcoma cell metastasis by suppressing MET via the mitogen-activated protein kinases/ERK kinase (MEK)–ERK pathway." (PMID 34202288, 2021). "Although LCN2 has been reported to be involved in iron homeostasis and immune regulation in various types of cancer, its function in osteosarcoma remains insufficiently studied, and its role as a downstream target of SPI1 in the regulation of ferroptosis has not been clearly elucidated." (PMID 40636695, 2025). "We hypothesized that Rhizoma Paridis total saponins (RPTS) exert anti-osteosarcoma effects by inducing ferroptosis through inhibition of the SPI1/LCN2 axis." (PMID 40636695, 2025). "Conclusively, human osteosarcoma HOS and U2OS cell-derived LCN2 contributes to inhibition of cellular migration through the MEK–ERK signaling pathway to downstream MET, and these findings imply an identified biomarker of LCN2 on anti-metastasis of osteosarcoma." (PMID 34202288, 2021). "The promotion of LCN2 expression to repress motility, invasion, and migration could be a potential target for anti-metastasis of osteosarcoma." (PMID 34202288, 2021). "Therefore, investigating whether RPTS induces ferroptosis in OS cells via the SPI1/LCN2 axis could provide valuable mechanistic insights and identify novel therapeutic targets to overcome ferroptosis resistance in osteosarcoma." (PMID 40636695, 2025). "Therefore, controversies related to the diverse effects of LCN2 remain, and especially in osteosarcoma are still unknown." (PMID 34202288, 2021). "In a study of osteosarcoma, LCN2 depletion promoted cell migration and invasion by modulating the MEK-ERK pathway, and the MEK inhibitor U0126 significantly decreased osteosarcoma tumor invasion and metastasis in vivo." (PMID 39248711, 2024). "To explore the underlying mechanisms of the anti-metastatic actions of LCN2 in osteosarcoma cells, we conducted a transcriptomic analysis of U2OS cells transfected with siRNA inhibiting human LCN2 for 24 h using RNA sequencing technology." (PMID 34202288, 2021). "Among them, MET is the most significantly upregulated gene in LCN2-knockdown cells and there are some reports regarding MET and osteosarcoma metastasis." (PMID 34202288, 2021).
osteosarcoma (continued). "Using manipulation of LCN2 in low LCN2 expression of HOS cells and high LCN2 expression of U2OS cells, we confirmed LCN2 contributing to the anti-metastatic property in human osteosarcoma cells regardless of originally high or low expressions." (PMID 34202288, 2021).
ovarian tumors (5 papers, 2009 to 2024). "The expression of immunoreactive NGAL (irNGAL) in ovarian tumors changes with disease grade and this change is reflected in the concentration of NGAL/LCN2 in peripheral blood, which allows LCN2 to be used as a biomarker of tumor progression." (PMID 38645429, 2024). "LCN2 is known as a marker from benign to pre- and malignant ovarian tumors and may be involved in progression of epithelial ovarian malignancies." (PMID 22203846, 2011). "Likewise, Lcn2 had a similar pattern with a 79- and 19-fold increased levels in ovarian tumor fluid and peritoneal ascites, respectively, consistent with their active secretion into surrounding fluids by tumor cells." (PMID 19936259, 2009).
pancreatic adenocarcinoma (5 papers, 2008 to 2023). "LCN2 has been shown to promote gemcitabine resistance in pancreatic adenocarcinoma cells in vitro and in vivo." (PMID 27168162, 2016).
polycystic kidney disease (5 papers, 2013 to 2023). A usually autosomal dominant and less frequently autosomal recessive genetic disorder characterized by the presence of numerous cysts in the kidneys leading to end-stage renal failure. "Viau and co-workers evaluated the function of Lcn-2 in the progression of kidney disease in two experimental in vivo models of polycystic kidney disease." (PMID 23861783, 2013). "We identify the LCN2 gene being over-expressed in IPF, CF, Schistosomiasis and SSc and the FBLN1 gene being under-expressed in CF, Myelofibrosis, Polycystic Kidney Disease and SSc and over-expressed in IgG4-related Disease." (PMID 33826640, 2021). "Lcn-2 induces cell proliferation via EGFR activation in non-inflammatory polycystic kidney disease models." (PMID 23861783, 2013).
pulmonary hypertension (5 papers, 2020 to 2026). Increased pressure within the pulmonary circulation due to lung or heart disorder. "Our results urge further exploration into the potential role of LCN2 in metabolic abnormalities associated with pulmonary hypertension." (PMID 39021353, 2024).
rheumatic diseases (5 papers, 2015 to 2024). "Our results clearly suggest that LCN2 is modulated and associated with inflammation in rheumatic diseases." (PMID 39403549, 2024). "At present, some evidence suggests the participation of LCN2 in the development of different rheumatic diseases." (PMID 39403549, 2024). "Although there are data pointing to the involvement of LCN2 in the joint pathophysiology of OA and RA, further studies are needed to elucidate its role in human development of such rheumatic diseases." (PMID 31443349, 2019). "Therefore, we open the possibility of using LCN2 serum levels as a biomarker of the inflammatory/disease activity in rheumatic diseases." (PMID 39403549, 2024). "However, more recently, other adipokines, such as progranulin, chemerin, lipocalin-2, vaspin, omentin-1 and nesfatin, have been recognized to display immunomodulatory actions in rheumatic diseases." (PMID 31443349, 2019).
skin cancer (5 papers, 2016 to 2025). "Therefore, POE might also be involved in reducing the risk of developing skin cancers in psoriatic patients by inhibiting LCN-2 expression." (PMID 39057409, 2024). "Since the KEGG pathway analysis of DEGs of K14-HPV8-CER skin tumours also suggest an enrichment of genes regulating IL-17 signalling comprising LCN2 and FOSL1, this strongly points to an important role of IL-17 signalling in HPV8-mediated tumorigenesis." (PMID 35406439, 2022). "MRNA levels of KLK6, LCN2 and FOSL1 were found to be significantly overexpressed in UV-induced skin tumours in K14-HPV8-CER mice compared to FVB/N wild-type skin, collected 24d after irradiation." (PMID 35406439, 2022).
acne (4 papers, 2014 to 2024). An inflammatory process of the sebaceous glands which is characterized by comedones, nodules, papules and/or pustules on the skin. "In acne lesions, S100 proteins may also be upregulated by lipocalin 2 (LCN2), which, promoting their keratinocyte secretion, aggravates psoriasiform skin inflammation in a Th17-dependent manner." (PMID 39744637, 2024). "The expression of AMPs human cathelicidin antimicrobial protein (hCAP18), lipocalin (LCN2), human beta-defensin 2 (hBD2), hBD3, S100A7 and S100A9 were found significantly upregulated in acne lesions in the Finnish patient group by RT-PCR." (PMID 25153527, 2014). "Based on microarray datasets GSE10432, GSE10433, and GSE11792, upregulated expression of LCN2, PTGES, and GDF15 might mediate sebocytes apoptosis; CCL2 and S100A7 could be related with “acne-flare” using isotretinoin for 1 week." (PMID 32685503, 2020). "Using isotretinoin for 1 week, LCN2, PTGES, and GDF15 were upregulated and might mediate sebocytes apoptosis and thus decreased sebum production; CCL2 originated from activated TNF signaling pathway and S100A7 could be related with “acne-flare”." (PMID 32685503, 2020). "In conclusion, this study exhibits that the upregulated expression of LCN2, PTGES, and GDF15 might mediate sebocytes apoptosis and thus decreased sebum production; while CCL2 originated from activated TNF signaling pathway and S100A7 could be related with “acne-flare” using isotretinoin for 1 week." (PMID 32685503, 2020).
acute myeloid leukemia (4 papers, 2014 to 2021). Acute myeloid leukemia (AML) is a group of neoplasms arising from precursor cells committed to the myeloid cell-line differentiation. "Thus, in this study we evaluated the expression of Lipocalin 2 (LCN) and BCL2L12, in newly diagnosed bone marrow samples taken from adult with Acute Myeloid Leukemia and to correlate their expression levels with clinical, laboratory data of the patients and prognosis and patient survival." (PMID 34319051, 2021).
bacterial pneumonia (4 papers, 2012 to 2024). Acute infection of the lung parenchyma caused by bacteria (e.g., Streptococcus pneumoniae, Haemophilus influenzae, Chlamydia pneumoniae, Mycoplasma pneumoniae, and Legionella pneumophila). "In another Gambian study, CRP, lipocalin-2 and vWF were associated with pediatric bacterial pneumonia using a composite diagnosis based on radiography, blood culture, and WBC count." (PMID 26366571, 2015). "For example, LTF, MPO, LCN2, and S100A9 are markers of neutrophil degranulation previously associated with bacterial pneumonia." (PMID 39409176, 2024). "Accordingly, other studies have shown that IL-1βinduced in response to extracellular bacterial pneumonia, plays a prominent role in infection-induced Lcn2 production, suggesting that it is likely that multiple cytokines can induce Lcn2 expression in response to inflammation." (PMID 23185529, 2012).
chronic pancreatitis (4 papers, 2008 to 2023). A chronic inflammatory process causing damage and fibrosis of the pancreatic parenchyma. "Pancreatic diseases such as acute and chronic pancreatitis and pancreatic ductal adenocarcinoma have in several cases been linked to increased lipocalin-2 expression." (PMID 37189804, 2023). "Comparing urinary lipocalin-2 amounts in small cohorts of focal chronic pancreatitis and pancreatic adenocarcinoma revealed ~2-fold higher levels in the latter." (PMID 37189804, 2023).
coagulopathy (4 papers, 2020 to 2025). "A study using a PE animal model showed that increased LCN2 plasma levels can be used as an indicator of renal complications and coagulopathies in PE." (PMID 39111712, 2024).
diabetic neuropathy (4 papers, 2021 to 2025). A chronic, pathological complication associated with diabetes mellitus, where nerve damages are incurred due to diabetic microvascular injury involving small blood vessels that supply these nerves, resulting in peripheral and/or autonomic nerve dysfunction. "Further research into the function of LCN2 will guide our understanding of its potential use as a diagnostic and therapeutic agent and will create new opportunities for improving the care of patients with diabetic neuropathy." (PMID 33613327, 2021). "LCN2 expression may be a useful early diagnostic biomarker for diabetic neuropathy; however, further validation using human samples derived from larger multi-institutional cohorts is needed." (PMID 33613327, 2021). "The small-molecule LCN2 inhibitors and neutralizing antibodies against LCN2 are important future directions for the treatment of diabetic neuropathy." (PMID 35966090, 2022).
Duchenne muscular dystrophy (4 papers, 2022 to 2025). Duchenne muscular dystrophy (DMD) is a neuromuscular disease characterized by rapidly progressive muscle weakness and wasting due to degeneration of skeletal, smooth and cardiac muscle. "One study investigating the role of lipoclin-2 as a potential therapeutic target in Duchenne muscular dystrophy (DMD) -induced bone loss in mice reported that deleting Lcn2, (by downregulation or blocking its activity) attenuated the loss of bone associated with DMD." (PMID 38516409, 2024). "Increased serum levels of Lcn2, as well as elevated mRNA levels in skeletal muscle, have been linked to the MDX mouse model of Duchenne Muscular Dystrophy." (PMID 37403010, 2023).
Encephalopathy (4 papers, 2019 to 2025). Encephalopathy is a term that means brain disease, damage, or malfunction. "Thorough investigation has demonstrated that LCN2 is involved in several neurodegenerative diseases, while more recent studies have shown that LCN2 is also instrumental for the progression of diabetic complications like encephalopathy and peripheral neuropathy." (PMID 33613327, 2021).
enteropathy (4 papers, 2016 to 2025). "Wild-type S. Typhimurium maintained higher fecal loads and elicited more pronounced enteropathy, while S.TmhilD loads declined during the 5 days of infection and caused attenuated enteropathy with delayed kinetics as judged by lipocalin-2 ELISA and by histopathology." (PMID 37651408, 2023). "Infection with both the wild type and the triple mutant resulted in high lipocalin-2 levels and severe enteropathy by day 4, indicating pronounced mucosal inflammation." (PMID 39966379, 2025). "Lower levels of inflammation were observed in mice infected with the quadruple mutant, with both lipocalin-2 and enteropathy (less edema) being significantly lower compared to the wild type." (PMID 39966379, 2025). "Because the present study regimen caused intestinal toxicity, we investigated the possibility that the extent of decline in serum LCN2 and MMP9 levels might also, in susceptible individuals, predict treatment-induced enteropathy, clinically presenting as diarrhea." (PMID 27461255, 2016).
Erythema (4 papers, 2019 to 2025). Redness of the skin, caused by hyperemia of the capillaries in the lower layers of the skin. "Our observations reveal a positive correlation between LCN2 protein levels in lesional skin and the severity of erythema, indicating its involvement in the inflammatory response of psoriatic skin lesions." (PMID 40369189, 2025).
gastric tumor (4 papers, 2012 to 2025). "Collectively, LCN2 expression develops gastric tumors associated with the epithelial phenotype and is reduced as the tumor progresses, ending up being undifferentiated." (PMID 35705840, 2022). "It is plausible that the overexpressed lipocalin-2 in tumor tissue released into the circulation may contribute to the elevated systematic level of lipocalin-2 supported by the direct correlation between elevated serum levels of lipocalin-2 and strong immunostaining grade in gastric tumor cells." (PMID 22640376, 2012).